BOK (BCL2 family apoptosis regulator BOK)
Diseases named in the same sentence as BOK in open-access papers (continued):
Sharing a sentence is not in itself a finding about the gene and the disease.
breast carcinoma (continued). "In addition, the BOK expression level was not significantly different across different stages of breast cancer." (PMID 40806384, 2025). "Consequently, to further investigate BOK’s role in the EMT process of breast cancer cells, this study employed the TGF-β-induced EMT process in MCF-7 cells, and the result suggested that BOK expression was downregulated in a time-dependent manner with the prolonged TGF-β treatment." (PMID 40806384, 2025). "However, BOK knockdown reverses this effect, thereby confirming that the ubiquitin-mediated degradation of BOK plays a role in regulating the EMT process and migratory capacity of breast cancer cells." (PMID 40806384, 2025). "In addition, we show that silencing of Mcl-1 but not BOK reduced the long-term growth of breast cancer cells." (PMID 29156771, 2017). "Interestingly, we observed elevated BOK mRNA but not BOK protein in our stable breast cancer cells." (PMID 29156771, 2017).
preeclampsia (5 papers, 2018 to 2025). Preeclampsia is a hypertensive disorder of pregnancy that is characterized by new-onset hypertension with proteinuria presenting after 20 weeks of gestation, and depending on mild or severe forms may initially present with severe headache, visual disturbances, and hyperreflexia. "Accordingly, increased BOK expression in these tissues was associated with trophoblast hyperproliferation and the development of preeclampsia." (PMID 33291826, 2020). "Moreover, in patients suffering from preeclampsia, a splice variant of BOK, BOK-P, was described." (PMID 33043006, 2020). "One of the identified biomarker genes, BOK is also involved in mitochondrial depolarization, in which studies report that this gene promotes mitochondrial fission in preeclampsia." (PMID 37994325, 2023). "Apart from cellular proliferation and apoptosis induction, several observations point toward an autophagy regulating role of BOK in preeclampsia." (PMID 33043006, 2020). "The Caniggia laboratory reported physiological BOK expression in proliferating trophoblast cells that is further increased in preeclampsia, where it contributes to the hyperproliferative state of the trophoblasts." (PMID 33043006, 2020). "In summary, our study uncovered a novel CER/BOK-induced regulation of mitochondrial fission and its functional consequence for heightened trophoblast cell autophagy in preeclampsia." (PMID 29463805, 2018). "Interestingly, a splice variant of BOK that lacks part of the 5′ UTR, the BH4, and part of the BH3 domain was reported in preeclampsia patients." (PMID 33291826, 2020). "In human preeclampsia, we reported that mitochondrial long-chain Cer buildup tilted placental mitochondrial dynamics towards mitochondrial fission, with smaller and more fragmented mitochondria, driven in part by increased expression of the Bcl-2 family member BOK." (PMID 41167398, 2025). "Moreover, we found that full-length PTEN-induced putative kinase 1 (PINK1) and Parkin, were elevated in mitochondria from PE placentae, implicating mitophagy as the process that degrades excess mitochondria fragments produced from CER/BOK-induced fission in preeclampsia." (PMID 29463805, 2018). "Besides cancer, BOK expression and regulation have been connected with preeclampsia, a placental disease that may occur during pregnancies and that is characterized by a reduced oxygenation of trophoblast cells, increased trophoblast cell death, and trophoblast hyperproliferation." (PMID 33043006, 2020).
lung carcinoma (4 papers, 2015 to 2025). "To analyze the role of BOK in lung cancer, we used mice harboring a lox-stop-lox-KrasG12D allele, in which the mutated Kras is expressed upon AdenoCre viral infection of the lungs." (PMID 35091677, 2022). "Based on the frequently observed genomic deletions of BCL-2-related ovarian killer (BOK) in cancer patients, we explored the function of BOK in a mutant KrasG12D-driven murine model of lung cancer." (PMID 35091677, 2022). "Taken together our data indicate that BOK supports tumor progression in Kras-driven lung cancer." (PMID 35091677, 2022). "Studying various cancer cell lines, we identified by Western blotting that the lung cancer cell lines A549 (adenocarcinoma), H226 (squamous cell carcinoma), and PC9 (adenocarcinoma) showed high variability in BOK protein levels, while all of them had comparably high BCL-B." (PMID 39996719, 2025). "Taken together, our data show that BOK promotes proliferation of tumor cells in mutant Kras-driven lung cancer and that, in contrast to common opinion, BOK genomic deletion does not represent a recurrent event in lung cancer." (PMID 35091677, 2022). "Furthermore, we show that the BOK locus is not genetically deleted in human lung cancer naïve samples." (PMID 35091677, 2022).
non-small cell lung carcinoma (4 papers, 2018 to 2025). A group of at least three distinct histological types of lung cancer, including non-small cell squamous cell carcinoma, adenocarcinoma, and large cell carcinoma. "BOK is downregulated in non-small cell lung cancer (NSCLC) and high BOK is associated with good prognosis in lymph-node positive patients." (PMID 29769323, 2018). "Similarly, in a study of non-small cell lung carcinoma, BOK inhibited the EMT process, served as a tumor suppressor, and attenuated the capacity of TGF-β to induce cellular migration." (PMID 40806384, 2025). "Notably, BOK functions as a tumor suppressor in non-small cell lung carcinoma by inhibiting EMT." (PMID 40806384, 2025). "It was also shown that BOK is downregulated in patients with late-stage compared to early-stage non-small cell lung carcinoma (NSCLC) and high BOK levels could predict extended patient survival." (PMID 33291826, 2020).
colorectal tumor (3 papers, 2018 to 2020). "In other words, the miR-1247-3p can inhibit apoptosis of colorectal tumor cells through targeting the BOK." (PMID 30056689, 2019). "We demonstrated that BOK protein levels in colorectal tumour were significantly decreased compared to their matched normal samples, suggesting that reduced BOK protein levels may contribute to carcinogenesis and tumour establishment." (PMID 29374142, 2018).
hepatocellular carcinoma (3 papers, 2020 to 2022). A malignant tumor that arises from hepatocytes. "The role of BOK in affecting cellular proliferation, cancer development, and progression was also reported in a chemical-induced hepatocellular carcinoma model in the mouse." (PMID 33043006, 2020). "On the other hand, a pro-tumorigenic role for BOK is reported in hepatocellular carcinoma where deletion of BOK is infrequent." (PMID 32335811, 2020). "Of note, TRIM28 and BOK levels were found to be negatively correlated in selected cancers such as hepatocellular carcinoma and kidney cancer." (PMID 33043006, 2020).
lymphoma (3 papers, 2018 to 2020). A malignant (clonal) proliferation of B- lymphocytes or T- lymphocytes which involves the lymph nodes, bone marrow and/or extranodal sites. "Alterations of BAX, BAK, or BOK have not been reported in human lymphoma; thus, loss/inactivation of BAX, BAK, or BOK either does not occur or is a rare event in human B cell lymphoma." (PMID 30671383, 2018).
melanoma (3 papers, 2020 to 2023). A malignant, usually aggressive tumor composed of atypical, neoplastic melanocytes. "Low expression of BOK in melanoma was positively correlated with prognosis, i.e., the prognosis is poorer when the expression is higher." (PMID 37745303, 2023). "In this current study, the result of q-PCR revealed that BOK was significantly down-regulated in melanoma tissues." (PMID 35387121, 2022). "BOK and CYLD were down-regulated, and CD14 and FASLG were up-regulated in melanoma samples, which were in accordance with the bioinformatics results." (PMID 35387121, 2022). "Links between BOK expression and patient outcome have not been reported in melanoma to date." (PMID 32858528, 2020).
lung adenocarcinoma (2 papers, 2022 to 2025). A carcinoma that arises from the lung and is characterized by the presence of malignant glandular epithelial cells. "To further explore the role of BOK, we used the mutant Kras-driven mouse lung adenocarcinoma cell line LKR10 to generate Bok-deficient cells by CRISPR/Cas9 (LKR10 Bok−/− and, as control, LKR10 LacZ)." (PMID 35091677, 2022). "In line with our discoveries, independent work has shown that experimental overexpression of BOK in A549 lung adenocarcinoma cell line inhibits migration and endothelial-mesenchymal transition (EMT)." (PMID 39996719, 2025). "Collectively, our data point towards a function of BOK in promoting the development of lung adenocarcinomas." (PMID 35091677, 2022).
multiple myeloma (2 papers, 2018 to 2025). "In addition, BOK expression has been observed to be deficient in several multiple myeloma cell lines." (PMID 40806384, 2025).
viral infection (2 papers, 2014 to 2022). "Golgi-fragmentation occurs upon experimental reduction of GA matrix proteins or overexpression of other proteins (BOK is an example); it has been described in viral infection, in infection with Legionella and with Shigella as well as with Toxoplasma (these are only examples)." (PMID 25068694, 2014).
bronchopulmonary dysplasia (1 paper, 2025). Bronchopulmonary dysplasia is a chronic respiratory disease that results from complications related to lung injury during the treatment of infant acute respiratory distress syndrome in low-birth-weight premature infants or from abnormal lung development in older infants. "Identifying pro-apoptotic proteins that BCL2 counteracts, such as BAX, BAK, and/or BOK, and unraveling their upstream regulators will provide further insights into AMF apoptosis mechanisms, which may be disrupted during impaired alveologenesis in bronchopulmonary dysplasia." (PMID 40492191, 2025).
COVID-19 (1 paper, 2023). A disease caused by infection with severe acute respiratory syndrome coronavirus 2. "A recent study reported that BOK levels were upregulated by the SARS-CoV-2 membrane protein (M), leading to apoptosis and lung edema in mice, which may open opportunities for BOK targeted interventions against COVID-19." (PMID 36289446, 2023).
endometriosis (1 paper, 2024). The growth of functional endometrial tissue in anatomic sites outside the uterine body. "Using clinical samples, we demonstrated that the protein levels of PERK, p-PERK, ATF6, GRP78, and BOK were decreased in endometriosis using clinical samples." (PMID 38549776, 2024). "Thus, downregulation of BOK in endometriosis might render endometriotic cells resistant to ER stress-induced apoptosis." (PMID 38549776, 2024).
injury (1 paper, 2021). Damage inflicted on the body as the direct or indirect result of an external force, with or without disruption of structural continuity. "Along these lines, BOK has been shown to promote cell death in a chemical-induced liver injury model." (PMID 33807047, 2021). "The BCL-2 family member BOK (BCL-2-related ovarian killer) has been described to modulate the unfolded protein response and to promote chemical-induced liver injury." (PMID 33807047, 2021).
liver cancer (1 paper, 2021). An epithelial or non-epithelial malignant neoplasm that arises from the liver. "A more detailed analysis of this protein in BC appears warranted, in particular as loss of BOK reportedly prevents liver cancer in mice." (PMID 34903710, 2021).
multiple sclerosis (1 paper, 2015). A progressive autoimmune disorder affecting the central nervous system resulting in demyelination. "Additionally, three were associated with neurological disorders or functions including SZ (rs4129585 at TSNARE1), multiple sclerosis (rs12644284 at TRIM2) and brain structure (rs12479254 at BOK)." (PMID 25990720, 2015).
neuroblastoma (1 paper, 2022). Neuroblastoma (NB) is the most common solid, extracranial childhood tumor. "While these reports have shown that loss of BOK affects a specific branch of UPR signaling, such as IRE1- or PERK-eIF2α-ATF4-signaling, our data indicate that BOK deficiency influences indeed all three UPR-signaling branches in the neuroblastoma-derived cell lines." (PMID 36060797, 2022). "To further investigate the role of BOK during ER stress, we used human SH-SY5Y neuroblastoma-derived ER stress reporter cell lines, which had been generated and extensively characterized in our laboratory." (PMID 36060797, 2022). "Of note, we did not observe increased levels of basal ER stress in the BOK-silenced neuroblastoma cells." (PMID 36060797, 2022).
ovarian carcinoma (1 paper, 2023). A malignant neoplasm originating from the surface ovarian epithelium. "These apoptotic-resistant ovarian cancer cells are significantly influenced by BOK, which probably contributes to the high recurrence rates of chemo-resistant disease." (PMID 37888203, 2023). "Specifically, extensions of the known BOK exons were mainly present in ovarian cancer cell lines." (PMID 37888203, 2023). "Current knowledge of ovarian cancer provides strong indications that not only establish BOK as an inducer of apoptosis in a BAX- and BAK1-independent manner, but also suggest that BOK can significantly influence the apoptotic response to chemotherapeutic drugs in ovarian carcinoma cells." (PMID 37888203, 2023).
pancreatic cancer (1 paper, 2025). "Furthermore, BOK knockdown in pancreatic cancer cells enhanced migration and invasion ability." (PMID 40806384, 2025). "Similarly, miR-296-5p targets BOK to participate in invasion and EMT in pancreatic cancer." (PMID 40806384, 2025).
prostate carcinoma (1 paper, 2023). A carcinoma that arises from epithelial cells of the prostate gland. "While our study has unveiled a comprehensive profile of novel circRNAs associated with the apoptosis-related BOK gene in human ovarian and prostate cancer cells, it is imperative to highlight potential avenues for future research in this field." (PMID 37888203, 2023). "Moreover, the potential of BOK circRNAs as diagnostic and prognostic molecular biomarkers could be elucidated in the future by assessing their expression in ovarian and prostate cancer patients’ tissue samples." (PMID 37888203, 2023). "The comprehensive understanding of the function of the novel BOK circRNAs function will aid in elucidating the possible need for such a wide range of circRNAs and their involvement in ovarian and prostate cancer." (PMID 37888203, 2023). "Prompted by the apparent scientific gap in circRNAs from apoptosis-related genes, such as BOK, we focused on the identification of novel BOK circRNAs in human ovarian and prostate cancer cells." (PMID 37888203, 2023). "Based on these, we aimed to explore the alternative circular transcripts of BOK in ovarian and prostate cancer in such depth that could be elucidated only by a high-throughput sequencing approach." (PMID 37888203, 2023).
Stroke (1 paper, 2020). Sudden impairment of blood flow to a part of the brain due to occlusion or rupture of an artery to the brain. "Therefore we hypothesized that BOK might play a role in stroke-induced cerebral neuronal apoptosis and that miR-149-3p regulates BOK expression." (PMID 33216728, 2020). "Therefore, this suggests that miR-149-3p sponging by DLX6-AS1 may lead to cerebral neuron I/R-induced impairments through upregulation of apoptotic BOK activity, which offers a new approach to the treatment of stroke impairment." (PMID 33216728, 2020).
uterine leiomyosarcoma (1 paper, 2023). "Specifically, genes such as PGR, TRIM22, BOK, NAALADL1, AFAP1L2, and ESR1 showed MSS values greater than 5 in uterine leiomyosarcoma samples." (PMID 38066476, 2023). "In addition, BOK, NAALADL1, and AFAP1L2 were identified as genes with MSS values greater than 5 in uterine leiomyosarcoma samples." (PMID 38066476, 2023).